EZR (ezrin)
Diseases named in the same sentence as EZR in open-access papers (continued):
Sharing a sentence is not in itself a finding about the gene and the disease.
lymph node metastasis (19 papers, 2012 to 2025). "Multivariate analysis showed that AJAP1-Ezrin+, histological grade, and lymph node metastasis were risk factors for OS (p = 0.021, p = 0.005, and p < 0.0001)." (PMID 35311087, 2022). "The pooled data of 4 studies showed significant association between high Ezrin expression and lymph node metastasis in esophageal cancer (OR = 2.07, 95% CI = 1.00–4.28, P = 0.050)." (PMID 29190988, 2017). "But pooled data on esophageal cancer showed significant association between high Ezrin expression and lymph node metastasis." (PMID 29190988, 2017). "Third, the pooled data from 6 studies showed that high Ezrin expression was significantly associated with lymph node metastasis in gastric cancer (OR = 3.96, 95% CI = 1.47–10.70, P = 0.007), with significant heterogeneity among studies (I2 = 85.0%, P = 0.000)." (PMID 29190988, 2017). "For esophageal cancer, Ezrin expression was associated with lymph node metastasis (OR 2.07, 95% CI 1.00–4.28) and overall survival (HR 1.49, 95% CI 1.17–1.89)." (PMID 29190988, 2017). "Enhanced immunoreactivity of all analysed proteins was found to be associated with the presence of lymph node metastases (ezrin, P = 0.047, moesin, P = 0.038, RhoA, P = 0.024, RhoB, P = 0.004 and Cdc42, P = 0.047)." (PMID 23420497, 2013). "Expression of EZR has been associated with invasiveness and lymph node metastasis of ESCC44,45." (PMID 30143675, 2018). "The expressions of ezrin and galectin-3 were both related with histological grade, deep myometrial invasion and lymph node metastasis (all P<0.05)." (PMID 28355349, 2017). "Ezrin overexpression was closely related with poor differentiation, late stage, and lymph node metastasis." (PMID 24182314, 2013). "Enhanced ezrin activation was linked with tumour grade, TNM stage and lymph node metastasis in GC." (PMID 36156321, 2023). "Ezrin over-expression was closely related with lymph node metastasis." (PMID 26933912, 2016). "Ezrin expression was associated with the tumor invasiveness and lymph node metastasis, but not with patient age and gender, or tumor size and degree of differentiation." (PMID 24959233, 2014). "Moreover, expression frequency of Ezrin protein increased significantly in lymph node metastasis and late clinical stages." (PMID 23039327, 2012). "Furthermore, its expression was found to be associated with the invasiveness of the cancer and lymph node metastasis, indicating that the expression of ezrin is an indication of tumor invasion and lymph node metastasis in patients, thereby resulting in a poor prognosis." (PMID 24959233, 2014). "High ezrin expression tended to be detected more frequently in cases with lymph node metastasis (62.5%) than in those without lymph node metastasis (44.3%)." (PMID 23357878, 2013). "The high expression of fascin-1, ezrin or paxillin was positively correlated with poor tumor differentiation, cervical lymph node metastasis (N+), and advanced clinical stage (III+IV) (P<0.05) but not sex or metastasis." (PMID 23209815, 2012). "However, only ezrinThr-567 was related with the presence of lymph node metastasis and the overall survival time of NSCLC patients, indicating that ezrin, especially ezrinThr-567, may prove to be useful as a novel prognostic biomarker of NSCLC." (PMID 24629131, 2014). "Notably, nuclear expression of ezrin was observed in 47.22 % of the cases with lymph node metastases, compared to 18.37 % in patients without nodal metastases (P = 0.004)." (PMID 23420497, 2013).
glioma (18 papers, 2010 to 2024). A benign or malignant brain and spinal cord tumor that arises from glial cells (astrocytes, oligodendrocytes, ependymal cells). "Accordingly, high levels of p‐Ezrin (T567) are associated with high‐grade gliomas and poor outcomes." (PMID 39239069, 2024). "Elevated levels of p-Ezrin (T567) are, accordingly, associated with high-grade glioma and with a poor patient prognosis." (PMID 37122733, 2023). "Ezrin has been implicated in the organisation of cell shape and migration as well as in the proliferation of glioma cells." (PMID 31382374, 2019). "Since then, ezrin upregulation has been associated with poor prognosis in numerous cancer types, including the association of ezrin with malignancy, and poor prognosis in glioma." (PMID 31382374, 2019). "Ezrin is also shown to increasesecretion of other molecules in neutrophils.Peroxiredoxin 1, an antioxidant and molecularchaperone, is overexpressed in many cancersincluding gliomas and its elevation is associatedwith poor clinical outcome." (PMID 28670517, 2017). "The upregulation of circGLIS3 in high‐grade gliomas can also be facilitated by exosomes, which facilitate tumor invasion, angiogenesis, and phosphorylation of Ezrin (T567)." (PMID 39239069, 2024). "Collectively, circGLIS3 contributes to high-grade glioma invasiveness via directly binding with p-Ezrin(T567) and contributes to glioma angiogenesis via exosome secretion." (PMID 34540823, 2021). "In this study, we confirmed that circGLIS3 can regulate Ezrin biological function in glioma through directly binding with p-Ezrin(T567)." (PMID 34540823, 2021). "To figure out the correlation between p-Ezrin(T567) expression and clinical-pathological features in glioma patients, we conducted tissue microarray analysis in different grades of 109 glioma tissues." (PMID 34540823, 2021). "Our findings indicate that circGLIS3 is upregulated in high-grade glioma and contributes to the invasion and angiogenesis of glioma via modulating Ezrin T567 phosphorylation." (PMID 34540823, 2021). "In summary, our study demonstrates that circGLIS3 is upregulated in high-grade glioma and contributes to the invasion and angiogenesis of glioma via modulating Ezrin T567 phosphorylation." (PMID 34540823, 2021). "Correlation between p-Ezrin(T567) expression and clinical–pathological features in 109 glioma patients." (PMID 34540823, 2021). "Ezrin mRNA expression level, total protein level, and p-Ezrin(F353) level are reported to contribute to glioma malignant phenotype." (PMID 34540823, 2021). "In conclusion, our study reveals that circGLIS3 promotes high-grade glioma invasion and angiogenesis by modulating Ezrin T567 phosphorylation." (PMID 34540823, 2021). "It is likely that the alteration of ezrin expression and redistribution within the tumour cells represents a pivotal element in the development of highly malignant and aggressive glioma." (PMID 31382374, 2019). "Due to its multiple functions as a cytoskeleton linker and a signalling protein, the role of ezrin in gliomas has been researched extensively for the last two decades." (PMID 31382374, 2019). "Our results showed that increased level of the ezrin protein was correlated with an increase in anchorage-independent growth of tumor cells, consistent with the previous finding in glioma cells." (PMID 20569470, 2010). "CircGLIS3 promoted invasion and tube formation of glioma through Ezrin T567 phosphorylation." (PMID 36463205, 2022). "CircGLIS3 was found to interact with T567-phosphorylated ezrin (p-EZR), but not with unphosphorylated ezrin, causing an increase in p-EZR, a protein that promotes cell migration and correlates with high-grade gliomas." (PMID 35681527, 2022). "It seemed that Ezrin was mainly phosphorylated by PKC in glioma." (PMID 34540823, 2021). "Interestingly, we also find a perivascular distribution pattern of p-Ezrin(T567) in glioblastoma, similarly with 87MG perivascular distribution of glioma satellite in nude mice." (PMID 34540823, 2021).
glioma (continued). "Mechanistically, we confirmed that circGLIS3 binds with p-Ezrin(T567) in glioma." (PMID 34540823, 2021). "We further explored the function of p-Ezrin(T567) in gliomas." (PMID 34540823, 2021). "We found that a higher IHC score of p-Ezrin(T567) might correspond to higher glioma WHO grade and to a shorter lifetime for patients." (PMID 34540823, 2021). "CircGLIS3 could increase the phosphorylation level of Ezrin T567 in glioma cells and then increase glioma cell motility." (PMID 34540823, 2021). "Besides, Pearson correlation analysis revealed that the expression of circGLIS3 was correlated with the level of p-Ezrin(T567) in glioma tissues." (PMID 34540823, 2021). "Future studies may reveal possible roles of ezrin or radixin phosphatases in the physiology of perisynaptic astrocytic ensheathment, glial activation (states), motility of activated astrocytes, and glioma invasiveness." (PMID 31382374, 2019). "Apart from high-grade malignant gliomas, ezrin may play an important role in low grade hamartomatous glial tumours as well." (PMID 31382374, 2019). "There are additional, isolated results indicating a role of ezrin in glioma malignancy." (PMID 31382374, 2019). "Garzon-Muvdi and colleagues demonstrated that in glioma cells, ezrin protein binds to the clusters of positively charged amino acids in carboxy-terminus domain of NKCC1, and mutation of the amino acids in these clusters reduced interaction between NKCC1 and ezrin." (PMID 24555568, 2014). "Taken together, these findings suggest that there is an increased interaction between p-NKCC1 and ezrin in GCs, which may promote glioma cell migration in the presence of TMZ." (PMID 24555568, 2014). "In addition, the upregulation of circGLIS3 is evident in high-grade glioma and exosomes can facilitate its secretion into the glioma microenvironment, facilitating tumor invasivity, angiogenic activity, and the phosphorylation of Ezrin (T567) phosphorylation." (PMID 37122733, 2023). "Besides, our results also showed the relation between Ezrin T567 phosphorylation and glioma." (PMID 34540823, 2021). "To figure out the correlation of circGLIS3 expression with p-Ezrin(T567) levels in glioma clinical samples, we stained both circGLIS3 and p-Ezrin(T567) on another tissue microarray with 58 NBT and glioma tissues." (PMID 34540823, 2021). "ERM (Ezrin, Radixin, and Moesin) proteins play an important role in cancer migration and invasion and interact with NKCC1 protein in glioma migration." (PMID 24555568, 2014). "Transwell assay showed that glioma cell motion could be restrained when inhibiting phosphorylation of the T567 residue of Ezrin with NSC305787, which is also observed in glioma cells after transfecting sh-circGLIS3 lentivirus." (PMID 34540823, 2021). "Here, we review data pertaining to potential molecular interaction partners of ezrin in astrocytes, with a focus on PKC and GRK2, and in gliomas and other diseases, to stimulate further research on their potential roles in glia-synaptic physiology and pathology." (PMID 31382374, 2019). "However, the 567 position threonine residue phosphorylation status of Ezrin in glioma has not been studied yet." (PMID 34540823, 2021). "Besides, we found that the expression of p-Ezrin(T567) was also positively correlated with glioma grade (P = 0.0116 and 0.0162), but not with sexual (P = 0.4086), age (P = 0.0585), and glioma recurrence (P = 0.1263)." (PMID 34540823, 2021). "Moreover, acidosis induces in glioma cells a compensatory up-regulation of the sodium–hydrogen exchanger isoform 1, protein that favour glioma invasion by influencing MMP activity and directly interacting with ezrin." (PMID 29300332, 2018).
colon carcinoma (17 papers, 2013 to 2025). "Altogether, bioinformatics analysis puts ezrin and caveolin-1 forward as highly ranked proteins significantly associated with vemurafenib resistance in colon cancer cells." (PMID 37629086, 2023). "The aberrant expression of ezrin is associated with the development and progression of several human cancers, such as hepatocellular carcinoma, lung cancer, breast carcinoma, pancreatic adenocarcinoma, colon cancer, osteosarcoma, rhabdomyosarcoma, and endometrial cancer." (PMID 25915860, 2015). "According to data from The Cancer Genome Atlas (TCGA), EZR expression is significantly decreased in colon cancer, with downregulation observed in 78% of colon adenocarcinoma (COAD) cases and 25% of rectal adenocarcinoma (READ) cases." (PMID 38909013, 2024). "Overexpression of the cell adhesion molecule L1 induces higher expression of ezrin-dependent PLOD2 by reducing SMAD2/3 in colon cancer, which stimulates cell proliferation, tumorigenesis, and liver metastasis." (PMID 39068670, 2024). "EZR activation has been reported to mediate hypoxia-induced autophagy in tumor cell self-renewal and colon cancer progression." (PMID 38706914, 2024). "Recent findings suggest that in colon cancer cells’ TGFβ signaling can regulate pro-apoptotic function by inhibiting the upregulation of ezrin phosphorylation in an Smad3-dependent manner." (PMID 33046439, 2021). "On the other hand we observed previously the presence of ezrin within the leading edge of colon cancer cells." (PMID 28333953, 2017). "Ezrin was shown to interact with neural cell adhesion molecule L1 and regulate the NF-κB signaling pathway in colon cancer." (PMID 26933912, 2016). "We demonstrate that ezrin phosphorylation at serine 66 selectively contributes to TRAIL-induced cell death regulation downstream of the TRAIL DISC in colon cancer cells." (PMID 26010871, 2015). "Previous studies showed that a range of cytokines, including interleukin 2 (IL-2), IL-8, IL-10, and insulin-like growth factor 1, inhibited ezrin expression in human colon cancer cells, whereas epidermal growth factor and IL-11 enhanced ezrin expression." (PMID 25915860, 2015). "Altogether these results argue against a physiological function for ezrin at the DISC level in colon cancer cells." (PMID 26010871, 2015). "Ezrin is a positive regulator of apoptosis in T-lymphoma cell line Jurkat, but a negative regulator in colon cancer cells." (PMID 26010871, 2015). "Altogether our results show that death receptor pro-apoptotic signalling regulation by ezrin can occur downstream of the DISC in colon cancer cells." (PMID 26010871, 2015). "The protein kinase PKN2, a potential tumor suppressor in colon carcinoma cell lines, was strongly up-regulated in the proteome analysis of both knockout cell lines, while Ezrin (EZR), a cytoskeleton protein with oncogenic potential, was moderately down-regulated." (PMID 36291816, 2022). "In addition, the expression levels of ezrin are increased in colon cancer cells displaying low TM expression." (PMID 27512995, 2016). "Furthermore, the association between the migration of colon cancer cells and the levels of TM and epithelial-to-mesenchymal transition (EMT) markers (fibronectin, vimentin and ezrin) was confirmed in HT29 and DLD-1 cells." (PMID 27512995, 2016). "In this study, TM suppression in colon cancer cells enhanced fibronectin, vimentin, and ezrin expression levels, which could increase the migratory capacity of colon cancer cells." (PMID 27512995, 2016). "Since ezrin has been demonstrated to be a component of the Fas DISC in lymphoid cells, we next checked whether ezrin was recruited in the TRAIL DISC in colon cancer cells." (PMID 26010871, 2015). "Like WT ezrin, the actin-binding deficient mutant R579A inhibited apoptosis induced by FasL and TRAIL, suggesting that inhibition of apoptosis induced by death receptor ezrin in colon cancer cells can occur independently of the cytoskeleton-binding properties of ezrin." (PMID 26010871, 2015).
colon carcinoma (continued). "These include a reduction in ERK signaling, diminished TGFβ1 production, decreased expression of the plasma membrane-cytoskeletal linker Ezrin, as well as attenuation of the paracrine effects of colon carcinoma-secreted factors on fibroblast migration and mitogenesis." (PMID 23755307, 2013). "In colon cancer, ezrin interacts with L1CAM and regulates NF-κB signaling." (PMID 23357878, 2013). "Bioinformatics findings prompted us to further examine the involvement of ezrin and caveolin-1 in mediating vemurafenib resistance in RKO colon cancer cells." (PMID 37629086, 2023). "In colon cancer cells, TGFβ and IGF1R signaling activates PKA through regulation of ezrin phosphorylation." (PMID 33046439, 2021). "The role of ezrin in regulating Fas- and TRAIL-induced apoptosis was then evaluated in colon carcinoma cells." (PMID 26010871, 2015). "Using ezrin phosphorylation or actin-binding mutants, we provide evidence that negative regulation of death receptor-induced apoptosis by ezrin occurs in a cytoskeleton- and DISC-independent manner, in colon cancer cells." (PMID 26010871, 2015). "In this respect, ezrin inhibitors might be further investigated within pre-clinical and clinical set-ups as an adjunct to BRAF inhibitors in treating BRAFV600E-mutant colon cancer." (PMID 37629086, 2023). "Our results demonstrate for the first time that TRAIL-induced cell death regulation by ezrin in colon carcinoma cells requires WWOX and occurs downstream of the TRAIL DISC, through regulation of ezrin phosphorylation on serine 66, owing to TRAIL's ability to induce PKA activation." (PMID 26010871, 2015). "Deficiency in WWOX expression in the liver cancer SK-HEP1 or the pancreatic Mia PaCa-2 cell lines as well as WWOX silencing or modulation of PKA activation by pharmacological regulators, in the colon cancer cell line SW480, abrogated regulation of TRAIL signalling by ezrin." (PMID 26010871, 2015). "WWOX requirement for ezrin-mediated TRAIL signalling regulation, as evidenced here, most likely provides a good explanation to the lack of regulatory function of ezrin in pancreatic or liver cancer cell lines, as opposed to colon cancer cells." (PMID 26010871, 2015). "Ezrin phosphorylation on threonine 567, although reported as a prerequisite for Fas aggregation and caspase-8 activation, did not enhance Fas ligand- nor TRAIL-induced cell death in colon cancer cells." (PMID 26010871, 2015).
rhabdomyosarcoma (17 papers, 2005 to 2022). A rare aggressive malignant mesenchymal neoplasm arising from skeletal muscle. "Ezrin, a cross-linker protein, plays an essential role in many metastatic phenotypes of cancer, including pediatric sarcomas, OS, and rhabdomyosarcoma." (PMID 35625426, 2022). "In a complementary DNA (cDNA) microarray analysis of highly and poorly metastatic rhabdomyosarcomas, ezrin was indicated to be a key regulator of metastasis." (PMID 20569470, 2010). "Here, we report that highly metastatic rhabdomyosarcoma (RMS) cells with high levels of Ezrin have elevated acetyl-H3-K9 and tri-methyl-H3-K4 as well as reduced DNA methylation at the Ezrin gene promoter." (PMID 20856924, 2010). "Ezrin, a cytoskeleton regulator protein, is a SIX1 direct transcriptional target in rhabdomyosarcoma." (PMID 34771571, 2021).